GPRC6A (G protein-coupled receptor class C group 6 member A)
Diseases named in the same sentence as GPRC6A in open-access papers (continued):
Sharing a sentence is not in itself a finding about the gene and the disease.
Insulin resistance (11 papers, 2008 to 2025). Increased resistance towards insulin, that is, diminished effectiveness of insulin in reducing blood glucose levels. "In the GPRC6a exon II KO mouse model constructed by Quarles, GPRC6A deletion was found to cause severe glucose intolerance and insulin resistance in mice." (PMID 36005612, 2022). "Human ucOCN can bind and activate human GPRC6A and promotes beta cell proliferation and insulin synthesis in human islets, while mutations or polymorphisms in human GPRC6A are associated with insulin resistance." (PMID 33284103, 2020). "This upstream peptide is similar to the pentadecapeptide WLGAPVPYPDPLEPR that is reported to activate GPRC6A in vitro and to improve fatty liver disease and insulin resistance after oral or intraperitoneal administration to a mouse model." (PMID 39399472, 2024). "Global deletion of Gprc6a in mice induces metabolic disorders, such as hyperglycemia, glucose intolerance, insulin resistance, hepatic steatosis, osteopenia, and feminization of males." (PMID 33428938, 2021). "With CS-treatment, both WT and GPRC6A KO mice developed insulin resistance as assessed by an insulin tolerance test (ITT)." (PMID 30979912, 2019). "Ablation of Gprc6a in mice results in obesity, glucose intolerance, hepatic steatosis, sarcopenia and insulin resistance, and deletion of Ocn, a natural ligand for GPRC6A leads to an identical phenotype to Gprc6a-/- mice." (PMID 29684031, 2018). "Similarly, GPRC6A−/− mice had elevated serum glucose levels glucose intolerance, insulin resistance and hepatic steatosis, as evidence by histological presence of fat and biochemical evidence of increase triglyceride content in livers of knockout mice." (PMID 19050760, 2008). "On the other hand, given that long-term GluOC administration induces insulin resistance in male mice because of an increase in circulating testosterone levels, it is likely that additional treatment with GluOC would be a more deteriorative additive to GPRC6A ablation." (PMID 33428938, 2021). "However, knockout of GPRC6A exon VI in mice showed neither glucose intolerance nor insulin resistance; however GPRC6A mice showed glucose intolerance when subsequently exposed to a high-fat diet." (PMID 36005612, 2022). "Whereas one group found glucose intolerance and insulin resistance as well as osteopenia and impaired osteoblast mediated bone formation in GPRC6a–/– mice, other groups could not detect such phenotypes." (PMID 32849661, 2020). "Furthermore, young GPRC6A exon VI KO mice did not exhibit glucose intolerance, insulin resistance, increased body fat or osteopenia under normal physiological conditions." (PMID 30979912, 2019).
metabolic syndrome (8 papers, 2008 to 2021). A cluster of metabolic risk factors for CARDIOVASCULAR DISEASES and TYPE 2 DIABETES MELLITUS. "Previous reports indicate that GPRC6A-/- mice exhibit lower bone mineral density and higher susceptibility to develop the metabolic syndrome than WT mice." (PMID 29194451, 2017). "GPRC6A knockout in mice results in metabolic syndrome, and the activation of GPRC6A stimulates the proliferation of ß-cells, increases peripheral insulin sensitivity, and protects against high-fat diet (HFD)-induced metabolic abnormalities." (PMID 33531899, 2021). "Global deletion of Gprc6a in mice is reported to result in a metabolic syndrome-like phenotype and conditional deletion of Gprc6a in pancreatic β-cell and skeletal muscle respectively impair insulin secretion and glucose uptake." (PMID 32350388, 2020). "There has been some debate as to the extent to which GPRC6A regulates metabolic function; one Gprc6a KO mouse strain displays manifestations of metabolic syndrome, increased serum glucose levels after an overnight fast as well as impaired insulin sensitivity." (PMID 26785252, 2016). "Moreover, mice deficient in the G protein-coupled receptor family C group 6 member A (GPRC6A), the putative receptor for ucOC, exhibited metabolic syndrome similar to that reported for OC−/- mice." (PMID 32544571, 2020). "GPRC6A’s unique regulation of β-cell, skeletal muscle and hepatic function may represent a new therapeutic target for treating disordered energy metabolism metabolic syndrome and type 2 diabetes." (PMID 32350388, 2020). "If so, activation of GPRC6A may provide a target to treat metabolic syndrome (MetS), type 2 diabetes (T2D), and non-alcoholic fatty liver disease (NAFLD)." (PMID 32636482, 2020).
Glucose intolerance (7 papers, 2008 to 2022). Glucose intolerance (GI) can be defined as dysglycemia that comprises both prediabetes and diabetes. "Both GPRC6A-/- and OCN-/- mice show similar phenotypes, including exacerbated glucose intolerance and impaired insulin secretion." (PMID 34489478, 2021).
Hepatic steatosis (6 papers, 2008 to 2024). Steatosis is a term used to denote lipid accumulation within hepatocytes. "We next examined how hepatocyte GPRC6A inactivation modulates the progression of HFD-induced hepatic steatosis." (PMID 33531899, 2021). "One potential mechanism is through the receptor Gprc6a since Gprc6a-/- mice also develop hepatic steatosis." (PMID 33776907, 2021). "We also found that the liver of GPRC6A−/− mice exhibited histological features of hepatic steatosis by H&E and Oil Red O staining." (PMID 19050760, 2008). "Together, these results demonstrate that GPRC6A is required for alleviating lipogenic activation and HFD-induced hepatic steatosis upon uncarboxylated osteocalcin treatment." (PMID 33531899, 2021).
Obesity (5 papers, 2015 to 2023). Accumulation of substantial excess body fat. "HE staining of the liver of 8-week-old mice showed that the loss of function of GPRC6A resulted in an abnormal liver structure, consistent with previous research suggesting that the loss of GPRC6A leads to obesity in mice due to impaired lipolysis." (PMID 36144181, 2022). "Global ablation of GPRC6A increases the susceptibility of mice to diet-induced obesity and related metabolic disorders." (PMID 33428938, 2021). "Another line of GPRC6A-deficient mice manifested an increased susceptibility to high-fat diet-induced obesity and related metabolic disorders." (PMID 33428938, 2021). "We found that adipocyte-specific Gprc6a deletion increased the susceptibility of mice to diet-induced obesity, with this effect being attributable to impaired lipolysis in adipose tissue and the consequent development of adipocyte hypertrophy." (PMID 33428938, 2021). "GPRC6A is involved in lipid metabolism in mice, and the loss of GPRC6A could promote diet-induced obesity by inhibiting the decomposition of fat." (PMID 36144181, 2022). "Our results thus suggest that constitutive GPRC6A signaling in adipocytes induced by physiologically relevant hormones and nutrition-related factors contributes to the prevention of obesity and related metabolic disorders." (PMID 33428938, 2021). "In summary, adipocyte-specific ablation of GPRC6A promoted the development of diet-induced obesity in mice by inhibiting lipolytic activity." (PMID 33428938, 2021). "This may be attributed to the normal fat percentage in our diets; the feeding period was only 5 weeks, and a former study has shown that a high-fat diet for 20 weeks induces obesity phenotypes in GPRC6A KO mice." (PMID 36144181, 2022). "Here, we examined the role of GPRC6A expression in adipose tissue in the development of obesity." (PMID 33428938, 2021). "GPRC6A is expressed in a wide range of tissues, suggesting it may serve a diverse range of physiological functions, and there is interest in GPRC6A as a potential novel target in therapeutic areas such as metabolism, obesity, and endocrine function." (PMID 25958858, 2015). "Our data indicate that loss of GPRC6A in adipocytes is largely, if not completely, responsible for the diet-induced obesity apparent in mice with systemic GPRC6A deficiency, suggesting that constitutive activation of GPRC6A signaling in adipocytes plays a key role in adipose lipid handling." (PMID 33428938, 2021). "It has been proposed that GPRC6A may sense amino acids in order to detect protein ingestion and modulate food intake accordingly and thus may be a useful target for pharmacological agents to treat obesity." (PMID 25958858, 2015).
Osteopenia (5 papers, 2008 to 2025). Osteopenia is a term to define bone density that is not normal but also not as low as osteoporosis. "Fine mapping of SNPs tightly linked to SNPs rs686708 and rs571296 and functional studies will be required to identify the causal variants in the GPRC6A region responsible for human osteopenia." (PMID 19874200, 2010). "The human relevance of these observations is supported by the association between SNPs rs686708 and rs571296 and reductions in spinal BMD in Caucasians, raising the possibility that GPRC6A polymorphisms may contribute to human osteopenia." (PMID 19874200, 2010). "The group of Quarles reported a complex dysmetabolic phenotype of their GPRC6A exon II KO mouse model, which included changes in systemic fuel metabolism, osteopenia as well as reduced testicular function in young mice." (PMID 30979912, 2019). "After binding with the osteocalcin receptor GPRC6A in muscle, it may influence osteopenia by promoting glucose metabolism, lipid metabolism, insulin secretion, expression and exercise-induced IL-6 secretion." (PMID 40771224, 2025). "GPRC6A null (GPRC6A−/−) mice exhibit multiple metabolic abnormalities including osteopenia." (PMID 19874200, 2010). "Theoretically, a primary decrease in bone formation and decreased buffering capacity for calcium, with consequent increased urinary expression of dietary calcium could account for the relationship between osteopenia and hypercalciuria in GPRC6A−/− mice." (PMID 19050760, 2008).
insulinoma (2 papers, 2016 to 2020). "INS-1 832/3 cells, a sub-clone of the INS-1 rat insulinoma cell line previously shown to express GPRC6A and to respond to OCN, were treated with vehicle or low doses of non-glycosylated and glycosylated ucOCN for 8 hr." (PMID 33284103, 2020).
pancreatitis (2 papers, 2021 to 2025). Inflammation of the pancreas. "Since the GPRC6A genotype was reported to be linked to pancreatitis, we tried to investigate the correlation between GPRC6A and EUS features in R-FD." (PMID 40827182, 2025). "GPRC6A is expressed in pancreatic acinar, ductal, and β-cells; it participates in endocrine metabolism; and it has been involved in pancreatitis using mouse models." (PMID 33517887, 2021).
type 2 diabetes (2 papers, 2018 to 2020). "New insights into G protein coupled receptor regulation of glucose metabolism by β-cells, skeletal muscle and liver hepatocytes identify GPRC6A as a potential therapeutic target for treating type 2 diabetes mellitus (T2D)." (PMID 29684031, 2018).
acute GVHD (1 paper, 2020). "In experimental acute GVHD, we found significantly decreased Gprc6a expression levels in the colon of allogeneic transplanted recipients at day + 15 after alloSCT during established acute GVHD; feasibly suggesting defects in calcium induced signaling during acute GVHD." (PMID 32849661, 2020). "We conclude that GPRC6a signaling in the alloSCT recipient but not in the alloSCT donor may play a role during acute GVHD." (PMID 32849661, 2020).
kidney damage (1 paper, 2022). "At the age of 55 weeks, almost all AA levels in urine of KO mice were significantly higher than that of WT mice, indicating that serious AA loss occurred in elderly GPRC6a KO mice, suggesting that, at the age of 55 weeks, GPRC6A deficient mice may have developed severe kidney damage." (PMID 36005612, 2022).
osteoporosis (1 paper, 2022). A condition of reduced bone mass, with decreased cortical thickness and a decrease in the number and size of the trabeculae of cancellous bone (but normal chemical composition), resulting in increased fracture incidence. "Furthermore, quercetin may exert biological effects on osteoporosis with metabolic disorders and may be associated with the GPRC6A/AMPK/mTOR signaling pathway." (PMID 35547008, 2022). "Thus, GPRC6A may provide a novel insight into the molecular basis of quercetin treatment for testosterone deficiency-induced osteoporosis." (PMID 35547008, 2022). "Previous research has found that GPRC6A(-/-) male mice exhibit osteoporosis and metabolic syndrome, such as increased weight and higher fat content, hyperglycemia, hyperphosphatemia, hypercalciuria, and feminization." (PMID 35547008, 2022). "As an essential modulated regulator of metabolism, GPRC6A may play a critical role in osteoporosis." (PMID 35547008, 2022).
parathyroid tumors (1 paper, 2023). "Furthermore, the GPRC6A expression was heterogeneous in the single parathyroid tumor: intensively positive cells were scattered through cells with weak membrane positive staining." (PMID 37065733, 2023).
prostate tumor (1 paper, 2015). "For some parameters, and depending on milk type, milk regimen could even exhibit slight protective effects towards prostate tumor progression by decreasing the expression of tumor-related markers like Ki-67 and Gprc6a." (PMID 25938513, 2015). "Prostate tumor progression was assessed by tissue histopathology examination, epithelial proliferation, stromal inflammation and fibrosis, tumor invasiveness potency and expression of various tumor markers relevant for each model (c-Fes, Gprc6a, activated Stat5 and p63)." (PMID 25938513, 2015).
proteinopathies (1 paper, 2025). "Overall, these findings uncover the crucial role of arginine sensing pathways in deregulating mTORC1 signaling in tauopathies and identify GPRC6A as a promising target for future therapeutics in tauopathies and other proteinopathies." (PMID 40848921, 2025). "Additionally, we showed that genetic repression or antagonism of GPRC6A signaling provides a novel therapeutic target for tauopathies and other proteinopathies." (PMID 40848921, 2025).
tauopathy (1 paper, 2025). Neurodegenerative disorders involving deposition of abnormal tau protein isoforms (tau proteins) in neurons and glial cells in the brain. "Furthermore, we observed increased GPRC6A and arginine in the brain, accompanied by increased mTORC1 signaling and decreased autophagy in a mouse model of tauopathy (Tau PS19)." (PMID 40848921, 2025).
tumor (9 papers, 2014 to 2023). "The putative OC receptor GPRC6A was detected in normal and tumor parathyroids at membrane or cytoplasmic level in cells scattered throughout the parenchyma." (PMID 37065733, 2023). "The knockdown of GPRC6A in PC3 cells was reported to significantly decrease tumor metastatic efficiency and invasiveness while increased expression of GPRC6A would enhance ERK and EMT signaling." (PMID 36110544, 2022). "In vehicle treated mice, implanted control PC-3 cells exhibited significant increases in tumor growth and weight compared to mice implanted with GPRC6A PC-3-sgRNA3 cells." (PMID 28659174, 2017). "Of the six genes (IGF2BP1, GPRC6A, IL37, CRCT1, SEMG1, and PSG7) for which we analyzed the differential expression between tumor tissues and healthy tissues in TCGA, four genes (CRCT1, PSG7, IL37, and IGF2BP1) showed notable differences." (PMID 36276966, 2022).
cancer (8 papers, 2013 to 2025). A tumor composed of atypical neoplastic, often pleomorphic cells that invade other tissues. "GPRC6A encodes an orphan G-protein-coupled receptor, mediates the non-genomic effects of testosterone and other anabolic steroids in multiple tissue, and it is a potential target for developing antagonists and agonists that would have broad applications in health and disease, including cancer." (PMID 25502083, 2015). "OCN signaling in peripheral systems, such as muscle, adipose tissue, and some cancer cells, is mediated by GPRC6A 30-33." (PMID 40765832, 2025). "Genes such as MAGEA3 and MAGEA6 contributed targets for 7 cancer types each, while genes such as UMODL1, NLRP4, MAGEC2, ANKRD30A, and GPRC6A contributed targets for only 1 cancer type." (PMID 27439771, 2016). "Gprc6a is a novel molecular target for regulating prostate growth and cancer progression." (PMID 25938513, 2015). "Additional candidates include GPRC6A, a Ca2+ activated G-protein coupled receptor proposed to be identical to mAR or the zinc transporter ZIP9 also proposed to fulfill the role of mAR in cancer cells." (PMID 27027435, 2016).
metabolic disorders (3 papers, 2017 to 2022). "However, given that GPRC6A is expressed in many tissues and responds to a variety of hormonal and nutritional signals, the cellular and molecular mechanisms underlying the development of metabolic disorders in conventional knockout mice have remained unclear." (PMID 33428938, 2021). "Our findings suggest the possibility to ameliorate metabolic disorders through GPRC6A and ApN signaling." (PMID 29194451, 2017). "Our findings imply the possibility to ameliorate menopause-induced metabolic disorder by GPRC6A and adiponectin signaling." (PMID 29194451, 2017). "Many of our findings are consistent with this study, which may indicate that GPRC6A is a potential therapeutic target for metabolic disorders in orchiectomy mice." (PMID 35547008, 2022). "On the basis of our previous observation that long-term oral administration of GluOC markedly reduced adipocyte size and improved glucose tolerance in WT mice, we examined whether GPRC6A signaling in adipose tissue might be responsible for prevention of metabolic disorders." (PMID 33428938, 2021).
degenerative diseases (1 paper, 2021). "Our study expands the spectrum of functions of GPRC6A, adds further evidence to the concept that the bone and liver regulate each other, and suggests that the pathogenesis of some degenerative diseases of energy metabolism may be more complex than anticipated." (PMID 33531899, 2021).
endocrine disorders (1 paper, 2019). "On these bases, GPRC6A attracted attention as a molecular target to pursue therapeutic strategies for metabolic and endocrine disorders." (PMID 31857654, 2019). "SHBG141–161 showed stimulating activity on GPRC6A, representing a template peptide with possible therapeutic use for metabolic and endocrine disorders." (PMID 31857654, 2019).
skeletal muscle disorder (1 paper, 2021). A disease involving the skeletal muscle tissue. "Considering this information, we hypothesized the presence of GPRC6A, instead of CaSR, in our model, which could be a possible drug target for skeletal muscle disorder." (PMID 34298895, 2021). "Considering all the information reported about GPRC6A, we hypothesized the presence of a GPRC6A receptor in human skeletal muscle as a potential drug target for skeletal muscle disorder." (PMID 34298895, 2021).
GPRC6A also shares sentences with these, for which no sentence is quoted: Hyperglycemia (2 papers); non-alcoholic fatty liver disease (2); adenocarcinoma (1); chronic pancreatitis (1); functional dyspepsia (1); Hypercalciuria (1); hyperphosphatemia (1); McCune-Albright syndrome (1); osteoarthritis (1); osteogenesis imperfecta type 1 (1); ovarian carcinoma (1); parathyroid adenomas (1); primary testicular failure (1); sarcopenia (1); type 2 diabetes mellitus (1).